TRPV1 (transient receptor potential cation channel subfamily V member 1)
Diseases named in the same sentence as TRPV1 in open-access papers (continued):
Sharing a sentence is not in itself a finding about the gene and the disease.
gastric adenocarcinoma (2 papers, 2023 to 2024). "A complete loss of TRPV1 expression in gastric adenocarcinoma was found in our study population." (PMID 39125864, 2024). "In tissue samples identified as gastric adenocarcinoma, there was no TRPV1 expression in either foveolar cells, parietal cells or chief cells." (PMID 39125864, 2024). "Using the Abcam anti-TRPV1 antibody (cat: ab3487), markedly reduced (or virtually absent) TRPV1 protein expression was found in gastric adenocarcinoma." (PMID 37240443, 2023). "For example, TRPV1 is expressed in normal or inflamed gastric mucosa, but is absent in gastric adenocarcinoma." (PMID 37240443, 2023). "TRPV1 expression was completely absent in gastric adenocarcinoma." (PMID 39125864, 2024). "For example, TRPV1 is expressed in benign gastric mucosa, but is absent in gastric adenocarcinoma." (PMID 37240443, 2023).
gastric tumor (2 papers, 2020 to 2025). "TRPV1 is abnormally expressed in gastric tumor cells, leading to the polymerization of cytoskeletal proteins, which, in turn, provides these cells with increased motility." (PMID 40232070, 2025). "TRPV1 significantly reduced gastric tumor size, number and peritoneal dissemination in vivo." (PMID 33008449, 2020).
gastric ulcer (2 papers, 2017 to 2021). An ulcerated lesion in the mucosal surface of the stomach. "Therefore, we believe that TRPV1 is closely associated with gastric ulcers." (PMID 34249268, 2021). "This study demonstrated the role of NO donor SNP to protect against gastric ulcer in rats, which was diminished by TRPV1 antagonist or vagotomy." (PMID 28522805, 2017). "In conclusion, we demonstrate that exogenous NO may participate in the vagal inflammatory reflex to improve gastric ulcer healing via TRPV1 S-nitrosylation." (PMID 28522805, 2017). "All these results indicate that NO might play a beneficial role in the gastric ulcer healing process via S-nitrosylation of TRPV1 on the vagus afferent fiber." (PMID 28522805, 2017). "Our results suggest that NO donor SNP alleviates acetic acid-induced gastric ulcer in rats via vagus nerve, while S-nitrosylation of TRPV1 may participate in this route." (PMID 28522805, 2017).
gastritis (2 papers, 2020 to 2024). Inflammation of the stomach. "Future preclinical functional and prospective clinical research investigating the specific correlations of TRPV1 expression in H. pylori-associated gastritis and gastric carcinogenesis is needed." (PMID 39125864, 2024). "In this observational histopathological study, TRPV1 expression was significantly higher in patients with H. pylori-associated gastritis compared with controls." (PMID 39125864, 2024). "TRPV1 expression was determined with immunohistochemistry and was significantly higher in patients with H. pylori-associated gastritis compared with controls (p = 0.002)." (PMID 39125864, 2024). "In summary, this observational histopathological study is the first to address TRPV1 expression in precursor stages of GC and H. pylori-associated gastritis, which is an individual risk for GC development." (PMID 39125864, 2024). "Significantly increased TRPV1 expression was demonstrated in H. pylori-associated gastritis and was even greater in patients with GIM and CAG, but its complete loss was seen in GC." (PMID 39125864, 2024). "The significant increase in TRPV1 expression in patients with H. pylori-associated gastritis compared with controls might be due to the pro-inflammatory roles of TRPV1." (PMID 39125864, 2024). "There are no data on the expression and function of the TRPA1 channel in gastritis and only little information is available on TRPV1." (PMID 32764237, 2020). "The main objective of this observational study was to assess TRPV1 expression in the gastric mucosa in patients with H. pylori-associated gastritis with and without GIM, CAG and intestinal-type adenocarcinoma." (PMID 39125864, 2024). "The role of TRPA1 and TRPV1 in gastritis might also be attributed to the mediation of inflammatory visceral hyperalgesia and abdominal pain." (PMID 32764237, 2020). "In addition, it remains to be established whether TRPV1-induced immune activation contributes to the further aggravation of H. pylori-gastritis or rather has mitigating effects." (PMID 39125864, 2024). "Therefore, our aim was to characterize a translationally relevant gastritis model using the irreversible sulfhydryl-group blocker IAA and to investigate the expression changes of TRPA1 and TRPV1 in this model." (PMID 32764237, 2020).
generalized tonic-clonic seizures (2 papers, 2015 to 2022). "Furthermore, we also measured TRPV1 immunofluorescence in brainstem structures involved with generalized tonic-clonic seizures and, similar as observed in the BLA, increased TRPV1 expression was detected in the dPAG and DLSC." (PMID 35203625, 2022). "Our results showed that systemic administration of TRPV1 agonist capsaicin (CAP, 40 mg/kg) directly induced tonic-clonic seizures (TCS) without PTZ induction." (PMID 25713512, 2015).
head and neck cancer (2 papers, 2022 to 2026). A primary or metastatic malignant neoplasm affecting the head and neck. "Moreover, oesophageal and head-and-neck cancer patients also overexpress TRPV1 and TRPA1 and these cancers are more promising targets for TRPV1 or TRPA1 agonist therapy." (PMID 35614079, 2022).
Heat Stroke (2 papers, 2020 to 2025). A condition caused by the failure of body to dissipate heat in an excessively hot environment or during PHYSICAL EXERTION in a hot environment. "Lately, we divulged a genetic link between TRPV1 mutations and two muscle pathologies, namely malignant hyperthermia (MH) and exertional heat stroke (EHS)." (PMID 33036239, 2020). "On the other hand, people with a deregulation of their core temperature after physical exercise, known as exertional heat stroke (EHS), may present TRPV1 variants." (PMID 39998081, 2025). "Heat stroke could appear not only due to the rise in the intramuscular temperature, but also due to the increasing proportion of slow muscles engaged during the effort, two parameters that trigger the activation of TRPV1." (PMID 33036239, 2020). "On the other hand, one could take advantage of the side-effects of TRPV1 agonists—namely hypothermia—to effectively manage pathologies inducing hyperthermia-like heat stroke, for which no approved drug currently exists." (PMID 39998081, 2025).
hepatic diseases (2 papers, 2022 to 2024). "However, the role of TRPV1 in other hepatic diseases may be in contrast with the results so far, thus evidencing the complexity of this matter." (PMID 35455971, 2022).
Hyperreflexia (2 papers, 2023 to 2025). Hyperreflexia is the presence of hyperactive stretch reflexes of the muscles. "On the other hand, elevated bladder AEA levels can also activate other off-target receptors such as the transient receptor potential cation channel subfamily V member 1 (TRPV1), which may evoke hyperreflexia and hyperalgesia and increase the micturition volume." (PMID 35647939, 2023).
Hypoglycemia (2 papers, 2019 to 2025). A decreased concentration of glucose in the blood. "Since vagus nerve activity increased as a response to hypoglycemia, we reasoned that this response may be mediated by TRPV1 fibers." (PMID 32232099, 2019). "However, whether TRPV1 fibers are not only necessary, but also sufficient for responses to hypoglycemia has not been examined previously." (PMID 32232099, 2019).
hypoxic ischemic encephalopathy (2 papers, 2021 to 2025). "Trpv1 KO mice experiments demonstrated that Trpv1 activation in astrocytes might be related to the severity of hypoxic ischemic encephalopathy, which is a serious complication at birth." (PMID 33806707, 2021). "Within hypoxic-ischemic encephalopathy (HIE), transient receptor potential vanilloid 1 (TRPV1) intensifies astrocyte activation and promotes the secretion of IL-1β by astrocytes via the JAK2-STAT3 signaling pathway and activation of NLRP3 inflammasomes." (PMID 40083546, 2025).
idiopathic pulmonary arterial hypertension (2 papers, 2019 to 2020). A sporadic form of pulmonary arterial hypertension (PAH) characterized by elevated pulmonary arterial resistance leading to right heart failure. "However, based on in vitro study, TRPV1 activation may aggravate idiopathic pulmonary arterial hypertension (IPAH)." (PMID 32316328, 2020). "The study of idiopathic pulmonary arterial hypertension (IPAH) pathogenesis revealed that vasoconstriction due to PASMC contraction and pulmonary vascular remodeling as the result of increased PASMC proliferation, growth, and migration are developed because of upregulation of TRPV1 channels." (PMID 31263706, 2019).
infertile (2 papers, 2012 to 2022). "The reduced expression of TRPV1 in spermatozoa of infertile patient samples with high ROS (ROS+) was reported for the first time." (PMID 36211461, 2022). "In addition, as TRPV1 ion channels contribute to the choice between cell survival and death during spermatogenesis in murine sperm, a decrease of sperm TRPV1 could be at least partly responsible for the oligospermia of infertile men." (PMID 23082196, 2012). "The consistent absence of detectable TRPV1 activity in infertile sperm, concomitant with the low levels of AEA detected in seminal plasma of infertile men could lead to a reduced fertilizing capacity of AEA." (PMID 23082196, 2012).
insulinoma (2 papers, 2020 to 2021). "TRPV1 mRNA expression was observed in rat INS-1, RINm5F cells, and INS-1E cells, and immunostaining displayed TRPV1 expression in INS-1E cells, rat islet endocrine cells, but not in β-cells from ZDF rats, NOD mice, or from isolated human islets or insulinomas." (PMID 35098034, 2021). "Human islets and human insulinoma cells do not express TRPV1." (PMID 32168890, 2020).
intestinal obstruction (2 papers, 2023 to 2024). Blockage of the normal flow of the intestinal contents within the bowel. "Early studies investigated the role of afferent neurons in the development of LPS-induced intestinal obstruction in mice through the interaction between TRPV1 and CGRP." (PMID 38731999, 2024). "Thus, afferent neurons that produce the neuropeptide CGRP and express TRPV1 play a crucial role in transmitting information from the periphery to the central nervous system during LPS-induced intestinal obstruction." (PMID 38731999, 2024). "Accordingly, blocking CGRP and TRPV1 may be a potential new strategy for treating endotoxin-induced intestinal obstruction." (PMID 38731999, 2024).
lymphoma (2 papers, 2017 to 2023). A malignant (clonal) proliferation of B- lymphocytes or T- lymphocytes which involves the lymph nodes, bone marrow and/or extranodal sites. "IL-31 was upregulated in mouse lymphoma, whereas its receptor Il31ra was persistently upregulated in Trpv1-expressing sensory neurons in mice with CTCL." (PMID 36520531, 2023). "Interleukin-31 (IL-31), T helper cell type 2- derived cytokine, activates a small subpopulation of primary sensory neurons expressing TRPV1, and TRPA1 through IL-31 receptor, and produced inflammatory and lymphoma-associated itch." (PMID 28515697, 2017).
metastatic carcinoma (2 papers, 2020 to 2023). A carcinoma which has spread from the original site of growth to another anatomic site. "Previous studies of bone pain in a metastatic cancer model have shown that the acidic microenvironment created by bone-resorbing osteoclasts activates transient receptor potential channels of the vanilloid subfamily member 1 (TRPV1)." (PMID 33322156, 2020). "In conclusion, in the presence of inflammatory metastatic carcinoma, doses of TRPV1 agonists high enough to activate TRPV1 in immune cells may have detrimental consequences; this effect may also partly explain the tumor-promoting action of TRPV1 agonists under certain conditions." (PMID 37371563, 2023).
metastatic melanoma (2 papers, 2018 to 2025). A melanoma that has spread from its primary site to another anatomic site. "Since TRPM8 activation has an opposing effect on TRPV1 activity, targeting TRPM8 may provide an effective alternative to suppress metastatic melanoma progression without side effects." (PMID 30483120, 2018).
mood disorder (2 papers, 2021 to 2025). A cognitive disorder a disturbance in which the person's mood is hypothesized to be the main underlying feature. "As a largely relevant nociceptor implicated in both pain and mood disorders, TRPV1 plays an essential role in the expression of CPDC." (PMID 34068557, 2021).
nephritis (2 papers, 2020 to 2022). Inflammation of renal tissue. "Intrarenal TRPV1-agonism by four consecutive bolus doses of capsaicin into the renal artery induced a sustained RSNA suppression that was severely impaired in rats suffering from experimental nephritis." (PMID 33070237, 2020).
pneumococcal infection (2 papers, 2021 to 2025). Infections with bacteria of the species streptococcus pneumoniae. "In this report, we demonstrated for the first time that TRPV1 and TRPV4 were involved in the development of invasive pneumococcal infections after establishment of nasal colonization by using knockout mouse strains." (PMID 34804016, 2021). "In conclusion, both TRPV1 and TRPV4 channels regulated the development of pneumococcal infections arising from nasal colonization in an adult mouse model." (PMID 34804016, 2021).
polycystic ovary syndrome (2 papers, 2016 to 2019). A disorder that manifests as multiple cysts on the ovaries. "The authors concluded that TRPV1 in neutrophils from patients suffering from polycystic ovary syndrome (PCOS) takes part in calcium entry and might be associated with calcium-entry dependent activation of neutrophils and release of pro-inflammatory cytokines." (PMID 31681615, 2019). "Interestingly, it was reported that NAC reduced oxidative stress and suppressed TRPV1 channel-mediated Ca2+ entry in neutrophils from patients with polycystic ovary syndrome (Köse and Nazıroğlu, 2015)." (PMID 26903865, 2016).
psychosis (2 papers, 2019 to 2024). "Another important mechanism is CBD’s effect on serotonin 5-HT1A receptors and TRPV1 channels, which are involved in neurocognitive processes related to psychosis." (PMID 39728841, 2024).
pterygium (2 papers, 2018 to 2022). A wedge-shaped fibrovascular lesion arising from the bulbar conjunctiva and extending to the cornea. "There was a sufficient amount of pterygium tissues from the 35 patients for further immunohistochemical analysis of TRPV1 and S100, which is a glial marker to visualize nerve fibers." (PMID 36555331, 2022). "There are a few reports about the expression of TRPV1 in pterygium." (PMID 36555331, 2022). "On the other hand, complete inhibition of the TRPV1+ stromal nerve fibers in pterygium may hinder the protective effects of neuropeptides such as VIP." (PMID 36555331, 2022). "Our findings, together with previous findings, suggest that inhibition of epithelial TRPV1 may inhibit the growth of pterygium." (PMID 36555331, 2022). "Hence, in the present study, we aimed to examine the possible relationship between SP, VIP and TRPV1 in cases with a recurrence of pterygium." (PMID 36555331, 2022). "In addition, they have documented that TRPV1 may mediate the mitogenic effects of growth factors and suggested that TRPV1 might be a potential therapeutic candidate in pterygium." (PMID 36555331, 2022). "The possible association between TRPV1 in nerve fibers and neuropeptides such as Substance P (SP) and Vasoactive Intestinal Peptide (VIP) in the recurrence of pterygium has not been examined before." (PMID 36555331, 2022). "However, the possible role of TRPV1, nerve fibers and neuropeptides in the recurrence of pterygium has not been examined before." (PMID 36555331, 2022). "Hence, the modulation of SP and neuronal TRPV1 activity rather than complete inhibition seems to be required for the prevention of pterygium as well as for safety." (PMID 36555331, 2022). "This strategy may provide a selective approach to inhibit TRPV1 upregulation and activation, which in turn suppresses angiogenesis, fibrosis as well as inflammatory processes in different pathophysiological conditions such as dry eye disease (DED), pterygium, and conjunctivitis sicca or red eyes." (PMID 30524369, 2018).
pulmonary hypertension (2 papers, 2019 to 2021). Increased pressure within the pulmonary circulation due to lung or heart disorder. "In summary, TRPV1-induced increases in [Ca2+]i in PASMCs can induce vascular contraction, proliferation and migration, which are enhancers of pulmonary hypertension." (PMID 31189399, 2019).
renovascular hypertension (2 papers, 2025). High blood pressure secondary to renal artery stenosis. "The present study investigated the proportion of mouse renal sensory neurons that were TRPV1-positive and the extent by which deletion of TRPV1 attenuated 2K1C renovascular hypertension." (PMID 41394927, 2025). "The premise of the current study was based on observations that chemical ablation of TRPV1-expressing renal sensory fibers lowered ABP in renovascular hypertension." (PMID 41394927, 2025). "A parallel experiment tested the extent by which deletion of TRPV1 channels in female mice altered 2K1C renovascular hypertension." (PMID 41394927, 2025). "Interestingly, both afferent renal nerve activity and arterial blood pressure were significantly attenuated in male Trpv1−/− rats after 2-kidney-1-clip (2K1C) renovascular hypertension." (PMID 41394927, 2025). "Therefore, the current study assessed the proportion of TRPV1 in mouse renal sensory neurons and tested whether deletion of TRPV1 altered renovascular hypertension in mice." (PMID 41394927, 2025). "We recently reported that the majority (∼85%) of renal sensory neurons in the rat are TRPV1-positive, and deletion of TRPV1 using Trpv1−/− rat reduced sympathetic nerve activity and ABP in 2K1C renovascular hypertension." (PMID 41394927, 2025). "Collectively, these findings suggest mice have both TRPV1 and non-TRPV1 renal sensory neurons, and TRPV1 channels do not contribute to renovascular hypertension in the mouse." (PMID 41394927, 2025).
rhinitis (2 papers, 2016 to 2018). An inflammation of the mucous membrane lining the nose, usually associated with nasal discharge. "TRPV1 is, in addition to being involved in cough and rhinitis, a major actor in pain and pain sensitivity, subsequently followed by increasing interest in the development of TRPV1 antagonists, both for cough treatment and for neuropathic pain disorders." (PMID 27483288, 2016).
Sensory neuropathy (2 papers, 2025). Peripheral neuropathy affecting the sensory nerves. "In the case of a TRPV1 vaccine, an autoimmune attack on TRPV1-positive neurons could cause sensory neuropathy." (PMID 41012116, 2025).
skin infection (2 papers, 2023 to 2025). An inflammatory process affecting the skin, caused by bacteria, viruses, parasites, or fungi. "Transient receptor potential cation channel subfamily V member 1 (TRPV1)+ neurons release calcitonin gene-related peptide (CGRP) during S. aureus-induced skin infections, which inhibits local neutrophil infiltration, decreases IL-1β and TNFα while enhancing IL-10 levels, aggravating the infection." (PMID 40005560, 2025). "Moreover, the neuropeptide CGRP seems to promote macrophage polarization towards an anti-inflammatory phenotype during skin infections, when S. aureus virulence factors (e.g., formyl peptides or HLα, a pore-forming toxin) activate TRPV1+ neurons." (PMID 40005560, 2025). "We used mice with TRPV1 channels selectively knocked out (TRPV1−/−) for skin infection modeling." (PMID 38129779, 2023). "Here, we hypothesized that TRPV1+ neurons increase the release of CGRP during S. aureus skin infection." (PMID 38129779, 2023). "Skin infection outcomes improved in whether TRPV1+ neurons were knocked out or eliminated in mice." (PMID 38129779, 2023).